HIF1A (hypoxia inducible factor 1 subunit alpha)
Diseases named in the same sentence as HIF1A in open-access papers (continued):
Sharing a sentence is not in itself a finding about the gene and the disease.
cancer (continued). "Similarly, HIF-1α activation fosters NF-κB-mediated proinflammatory gene expression in activated innate immune cells such as macrophages and neutrophils, although it has also been reported that HIF-1α can inhibit NF-κB activity in cancer cells." (PMID 37372061, 2023). "The hypoxia-inducible factor-1α (HIF-1α), a key player in the adaptive regulation of energy metabolism, and the M2 isoform of the glycolytic enzyme pyruvate kinase (PKM2), a critical regulator of glucose consumption, are the main drivers of the metabolic rewiring in cancer cells." (PMID 37305566, 2023). "Noticeably, HIF1a stabilization can increase due to drug-induced EMC stiffness in breast cancer, which might implicate that mechanical stimuli should be considered when understanding the genetic response in 3D cancer cultures." (PMID 36769044, 2023). "Thanks to its ability to reduce angiogenesis by blocking VEGFA and HIF1α in IH, its high potential for use in cancer therapy is clearly indicated, since hypoxia and subsequent activation of the expression of HIF-dependent proteins play a vital role in cancer progression." (PMID 37446271, 2023). "Therefore, MMP-17 transcription under hypoxia could be regulated directly by HIF-1α and through SLUG in these types of cancer." (PMID 38069210, 2023). "Thus, this study uncovers a novel oncogenic mechanism in which TET1 promotes oncogenesis and cancer progression through a non-enzymatic interaction between TET1 and HIF1α in hypoxia, providing novel therapeutic targeting implications for cancer." (PMID 37020036, 2023). "Although hypoxia-inducible factor-1α (HIF-1α), expressed in response to hypoxia, can induce Tregs and bind to the promoter region of the FOXP3 to promote transcription (22988108), it contributes to the development of an immunosuppressive TME by enhancing cancer-promoting immune cell functions." (PMID 36768924, 2023). "The results indicate that curcumin could effectively inhibit the growth and migration of hepatocarcinoma cells by inducing cancer cell apoptosis, blocking the cancer cell cycle in the S phase, and reducing the expression of STAT3, VEGF, and HIF-1α signaling pathways." (PMID 37333486, 2023). "Metabolites can regulate chromatin or protein acetylation (e.g., c-MYC, HIF-1α, GAPDH, PKM2, PEPCK, 6PGD, ACLY, LCAD, and BCAT2), histone succinylation, butyrylation, lactylation, phosphorylation, citrullination, and itaconation, and further contribute to cancer progression." (PMID 36831413, 2023). "Under physiological conditions, HIF-1α can be quickly hydroxylated and degraded by PHD2; however, multiple factors involved in TAM may modulate PHD2 activity to inhibit HIF-1α degradation, leading to the maintenance of HIF-1α protein, and promote aerobic glycolysis in cancer cells." (PMID 37153758, 2023). "Therefore, treatment deintensification could not be appropriate for the sub-group of HPV-positive oropharyngeal SCCs with HIF-1α overexpression, due to their unfavorable prognosis similar to HPV-unrelated cancers." (PMID 37445908, 2023). "The crude Astragalus saponins extracted from Astragalus membranaceus (Fabaceae) exhibited anti-cancer effects against colon and gastric cancer at 80 and 50 μg/mL, respectively, via inhibiting angiogenesis-inducing signaling pathways, including VEGF, bFGF, HIF-1α, and PI3K/mTOR/Akt." (PMID 36984763, 2023). "Sirtuin 3 (SIRT3)-dependent ROS production and HIF-1α stabilization upregulates the expression of glucose transporter GLUT1 and lactate transporter monocarboxylate transporter-4 (MCT4) in CAFs, thereby shuttling lactate from CAFs to cancer cells to promote anabolic processes and cell growth." (PMID 35884382, 2022). "Additionally, Se inhibits the activity of HIF-1α, HIF-2α, and VEGF in cancer cells." (PMID 36547898, 2022).
cancer (continued). "Cancer stem cell properties play critical roles in tumorigenesis, progression, and therapy, and SRg3 inhibits self-renewal activity in breast stem-like cancer cells by blocking Akt-induced HIF-1α activation and inhibiting HIF-1α-regulated expression of Bmi-1 and Sox-2." (PMID 36278171, 2022). "In cancers where c-Myc is overexpressed, its activity is not affected by HIF-1α." (PMID 35163079, 2022). "Moreover, between distinguished age groups, cancer cases differed in EPAS1 and HIF1A." (PMID 36230822, 2022). "Importantly, we demonstrate that STIL plays a versatile role in multistage tumorigenesis through the HIF1α-STIL-FOXM1 axis, and therefore may serve as a promising target for cancer therapy." (PMID 35365182, 2022). "We speculate that this is because HNK reduces the expression of HIF-1α protein, which in turn inhibits the transcription of key molecules GLUT1, HK2, and PDK1 on the glycolysis link, resulting in a decrease in the glycolysis level of cancer cells." (PMID 35350760, 2022). "Moreover, the remaining high HIF‐1α protein levels may antagonize HIF‐2α, a phenomenon that has been well characterized in cancer cell lines." (PMID 35014036, 2022). "Therefore, the development of therapeutic tools targeting HIF-1α without side effects is urgently needed for refractory cancers with radiation resistance." (PMID 35743281, 2022). "The immune system-related pathways ErbB, HIF1a, NF-kB, FoxO, JAK-STAT, Wnt, Notch, cell cycle, PI3K–AKT, RAP1, calcium signaling, cell junctions and adhesion, actin cytoskeleton regulation, and cancer pathways are among those that may be significant, according to the overall analysis." (PMID 36675976, 2022). "Consistently, another group recently reported that USP29 promotes aerobic glycolysis via stabilizing HIF1α to mediate sorafenib resistance in HCC cell lines, suggesting that USP29 may play a key role in the regulation of aerobic glycolysis in different cancer types." (PMID 35307036, 2022). "In the pathway of central carbon metabolism in cancer, SIRT6 could directly inhibit hypoxia-inducible factor 1α (HIF-1α), and SIRT3 could inhibit HIF-1α by repressing HIF-1 signaling, which then affected metabolic process such as glycolysis and tricarboxylic acid (TCA) cycle." (PMID 35136826, 2022). "Moreover, HIF-1α also regulates the expression of both MCT1 and LDH-A in cancer cells." (PMID 35847943, 2022). "In addition, the combination of GLUT inhibitors with GLUT signaling pathway inhibitors (e.g., Akt, mTOR, PI3K, HIF-1α, and AMPK) could be a new direction for cancer therapy." (PMID 36230492, 2022). "HIF1α (HIF1A) is a known response element activated during times of decreased oxygen availability and is highly regulated at the protein level, responding to hypoxia through transcriptional regulation of genes that affect metabolism, and is interconnected with PI3K signaling and cancer." (PMID 36077565, 2022). "However, Hu and colleagues discovered for the first time that the HIF-1α is responsible for the control of glycolytic gene transcription and, as a result, that it stimulates the glycolysis pathway in cancer progression, whereas the HIF-2α is not responsible." (PMID 35592530, 2022). "MDR not dependent on efflux pumps can also develop in cancer cells via activation of anti-apoptotic cellular mechanisms including elevated expression of the B-cell lymphoma 2 (Bcl-2) gene and inhibition of pro-apoptotic signals, or via HIF-1α and NF-κB." (PMID 36153528, 2022). "The proteomic screening of cancer cells treated with OA has revealed that it downregulates several factors, such as mitochondrial uncoupling protein 2 (UCP2), MMP-2, MMP-9, PKM2, superoxide dismutase 2 (SOD2), hypoxia inducible factor 1 alpha (HIF-1α), and PROX1." (PMID 36139025, 2022). "Hif-1α has not been reported to be implicated in the ROS and HIF-related cancer signal pathways." (PMID 36147561, 2022).
cancer (continued). "It is also known that HIF‐1α triggers mitophagy as an adaptive response to hypoxia through BNIP3 activation, suggesting that the prevention of mitophagy and the triggering of mitochondrial hyperplasia are favored in CI‐defective cancer models where HIF‐1α destabilization occurs." (PMID 34606156, 2022). "In addition, HIF-1α activates the hedgehog signaling pathway, which helps in EMT of cancer cells." (PMID 36014432, 2022). "PERK and IRE1, through their inhibitory effects on HIF-1α stability and transcriptional activity, could contribute the transition from HIF-1 to HIF-2 signaling in both endothelial and cancer cells that is observed during prolonged hypoxia, and this allows for a better adaptation to this insult." (PMID 36230792, 2022). "Many anticancer drugs induce oxidative damage as the primary mechanism through which to kill cancer cells, and the reduced capacity for ROS production under hypoxic conditions reduces the efficacy of these drugs, likely mediated by the downregulation of oxidative phosphorylation (OXPHOS) by HIF-1α." (PMID 35814435, 2022). "Therefore, we speculate that UFL1 and BRE1B are also E3 ligases involved in the ubiquitination degradation of HIF-1α, while HNK promotes the ubiquitination degradation of HIF-1α protein by UFL1 and BRE1B in cancer cells." (PMID 35350760, 2022). "However, no information regarding the role of HIF-1α on NPHP3-associated PC formation and cancer cell survival has been reported." (PMID 36498831, 2022). "There are also reports showing no crosstalk but antagonism between AMPK and HIF-1α in cancer cells." (PMID 35300979, 2022). "Although the cancer preventive activity of carvedilol is independent of β-blockers, we envision whether the anticancer activity of carvedilol is related to HIF1α, which is a major topic for further research in the future." (PMID 35860430, 2022). "Constitutive activation of HIF-1α is common in human cancers, regardless of oxygen tension." (PMID 35251493, 2022). "Furthermore, HIF-1α has been shown to translocate to the nucleus and interact with p300/cyclic adenosine monophosphate (cAMP) response element-binding protein (CREB)-binding protein (CBP) to regulate the transcription of its target genes in cancer." (PMID 35547748, 2022). "Therefore, it could be deduced that the differential compounds might help to treat cancer by acting on MAPK8 and HIF1A." (PMID 34335821, 2021). "HIF-1α appears to be preferentially expressed in CCA tissues, rather than in the neighboring normal biliary epithelium, and being such a relevant element in sustaining tumor chemoresistance and immune evasion, many hypoxia-targeting strategies are now under investigation for cancer therapy." (PMID 34638259, 2021). "HIF-1α can be also activated in hypoxia-independent manner in response to growth factors and cytokines stimulation, which activate signaling pathways such as Ras/MAPK, PI3K (phosphoinositide 3-kinase)/AKT or NF-κB (nuclear factor-kappa B), known to be often upregulated in cancer cells." (PMID 33918883, 2021). "The HIF-1α protein expression is absent in healthy tissue but raises up to 53% of cancers." (PMID 34436498, 2021). "In addition, CTP/CDDP could block HIF-1α/MMP9 pathway and promote RKIP expression in hypoxic cancer cells, thus inhibiting the EMT process and enhancing the anti-metastatic efficacy." (PMID 34399762, 2021). "Thus, the PH domain of PLD isozymes might be useful in the development of therapeutics targeting HIF-1α and FAK in cancers." (PMID 34471223, 2021). "Some genes are regulated only by HIF-2α and not HIF-1α in cancer." (PMID 34012919, 2021).
cancer (continued). "Furthermore, in cancer cells TGF-β is involved in many other signaling pathways, such as PI3K/Akt or MAPK, which, in turn, regulate redox-sensitive transcription factors, such as NF-kB or HIF-1α." (PMID 34205678, 2021). "Moreover, ATM is activated by hypoxia, and stabilizes the transcription factor HIF1α by direct phosphorylation or via the TRAF6/H2AX/HIF1α signaling axis, which could significantly increase cancer survival, invasion, and metastasis." (PMID 34070860, 2021). "Interestingly, hypoxia stabilizes HIF-1α and promotes the glycolytic phenotype in cancer cells whereas, in the surrounding nontumor tissue, the prolonged lack of O2 inhibits regular cell function." (PMID 33815663, 2021). "Trifluoperazine (TFP), as an inhibitor of DR2, promotes the degradation of HIF1a.Thus, DR2 may promote the progression of psychological stress-induced malignancies by activating the oxygen-independent HIF1a pathway, while TFP may serve as a potential therapeutic option for cancer patients." (PMID 34988010, 2021). "AHR and HIF-1α are not oncogenes but are crucial regulators of transcription programs in the microenvironment as sensors/responders to microenvironment conditions in both cancer and immune cells." (PMID 34572746, 2021). "Overall, these results underlined the significance of ERK-dependent phosphorylation of HIF-1α for the transcriptional response to hypoxia as well as the prospect of TAT-ETD peptides or their peptidomimetics as highly selective and isoform-specific inhibitors of the HIF-1 pathway in cancer cells." (PMID 33499237, 2021). "In addition to controlling glucose metabolism, PKM2 also regulates hypoxia-inducible factor-1α (HIF-1α), β-catenin (β-cat), epidermal growth factor (EGFR), signal transductors, transcriptional activators 3 (STAT3), and other cancer-related factors, thereby promoting cell growth and proliferation." (PMID 33905408, 2021). "It has been noted that there is an interactive loop that leads to increased cancer-like stemness, proliferation, metastasis, chemo-resistance, angiogenesis, and immunosuppression, wherein it simultaneously mediates major oncogenic pathways from BMP/Smad to HIF1α and TGFb." (PMID 35002707, 2021). "Moreover, it was also reported that cancers with high malignant potential such as triple‐negative breast cancer show HIF‐1α expression even under normoxic environment." (PMID 33773069, 2021). "Additionally, miR-200c inhibits HIF-1α and VEGF expression in U251 and A549 cancer cells." (PMID 33673143, 2021). "In this study, we aimed at determining the potential role of HIF-1α in the detection, signaling, and repair of DNA Double-Strand-Breaks (DSBs) in response to both irradiations, under hypoxia, in two HNSCC cell lines and their subpopulations of Cancer-Stem Cells (CSCs)." (PMID 34359734, 2021). "Thus, this study aimed to clarify a potential involvement of HIF-1α in the detection, signaling, and repair of DNA Double-Strand-Breaks (DSBs) in response to both irradiations, in two HNSCC cell lines and their subpopulations of Cancer-Stem Cells (CSCs)." (PMID 34359734, 2021). "Meanwhile, it will be interesting to see whether known transcription factors that regulate AXL synthesis (i.e., activator protein AP1, YAP/TAZ/TEAD, and HIF1α) can mediate the predominant activation AXL and promote EGFR-TKI-specific resistance trajectory in chemoresistant cancer cells." (PMID 33850249, 2021). "HIF-1 is essential not only for cancer and inflammatory diseases but also for body homoeostasis; HIF-1α knockout in mice is embryonically lethal at day E11 due to cardiovascular malfunctions and neural tube defects, whereas HIF-1α conditional knockout mice show various defects in this regard." (PMID 34621018, 2021). "Hence, in response to this hypoxia (i.e., lack of oxygen), cancer cells develop a hypoxic response via the hypoxia response transcription factor HIF1A." (PMID 34500819, 2021).
cancer (continued). "Furthermore, it could be shown by us and others that the transcription factor hypoxia-inducible factor 1α (HIF-1α) plays a role for MDSC function during pregnancy and cancer." (PMID 35111157, 2021). "Moreover, HIF-1α and HIF-2α could bind to hypoxia-responsive elements (HREs] in the promoter of Pref-1 and increased Pref-1 transcription in cancer cells." (PMID 34229599, 2021). "For example, collagen prolyl 4-hydroxylases (P4Hs), essential enzymes in the synthesis of collagens and collagen lysyl hydroxylases (PLOD2) required for ECM stiffness, are induced in cancer cells by exposure to hypoxia, which is dependent on HIF-1α, but not HIF-2α." (PMID 34202979, 2021). "For example, 2-methoxyestradiol (Panzem) inhibits HIF-1a protein synthesis and transcriptional activity has been used in combination with bevacizumab (VEGF mAb) in a Phase II clinical trial for metastatic carcinoid neuroendocrine tumor, result in reduced the tumor size in 68% of cancer patients." (PMID 35127700, 2021). "The low binding affinities indicate that digoxin does not induce apoptosis and autophagy in human cancer cells by targeting HDACs or IAPs directly, but it may mediate these activities through the HIF-1α, NKA, and NF-κB signaling pathways." (PMID 34208576, 2021). "Meanwhile, we provided evidence showing the importance of Nrf2 and its downstream target HIF1α in arsenic-induced metabolic shift from mitochondrial TCA cycle to glycolysis and the generation of the cancer stem-like cells, which supports the oncogenic role of Nrf2 in cancer development." (PMID 35052581, 2021). "In non-cancer patients, HIF-1α may have beneficial effects (e.g., muscle regeneration), but in oncologic patients it may promote cancer progression and recurrence." (PMID 34572400, 2021). "However, at least in our DGC cell line models, cancer cell lines did not affect the stability of HIF-1α and HIF-2α in the fibroblasts, suggesting that other mechanisms direct glycolytic reprogramming of the fibroblasts cocultured with 44As3 cells." (PMID 32555715, 2020). "HIF-1α induces angiogenesis and glycolysis by activating the expression of vascular endothelial growth factor (VEGF), glucose transporter (Glut), and glycolysis-related enzymes to control the transfer of oxygen and nutrients and improve the growth and proliferation of cancer cells." (PMID 32211041, 2020). "Thus, HIF-1α is the first driving force for cancer development, organizing the energy supply in OSCC under normoxic as well as hypoxic conditions." (PMID 32846951, 2020). "It is widely accepted that COX-2 has an important role in the stimulation of inflammation and tumorigenesis in hypoxic cancer cells, and the COX-2-selective inhibitor has been considered a potential candidate which can disturb the angiogenic signaling cascade upstream of HIF-1α-VEGF expression." (PMID 32273947, 2020). "Accordingly, after CoCl2 treatment, we could see an accumulation of HIF1α at the protein level, but not at the RNA level in U87-MG cancer cells." (PMID 32792639, 2020). "On cancer cells from various origins, it has been shown that DCA, a PDK inhibitor currently studied in clinical trials, decreased HIF-1 activity, resulting in a reduced expression of HIF-1α target genes including pro-angiogenic factors and a decreased tumor angiogenesis." (PMID 33076309, 2020). "Moreover, in TNBC cells, DHA decreased HIF1α transcriptional activity and expression of its targets glucose transporter 1 (GLUT 1) and lactate dehydrogenase (LDH), which are key mediators of glycolytic metabolism in cancer cells." (PMID 33123546, 2020). "Therefore, HIF-1α and VEGF are ideal biomarkers for cancer therapy and prognostic evaluation." (PMID 32375802, 2020).